RNFT1 (ring finger protein, transmembrane 1)
Description:
E3 ubiquitin-protein ligase that acts in the endoplasmic reticulum (ER)-associated degradation (ERAD) pathway, which targets misfolded proteins that accumulate in the endoplasmic reticulum (ER) for ubiquitination and subsequent proteasome-mediated degradation. Protects cells from ER stress-induced apoptosis.
Synonyms: PTD016
Tractability: Antibody: UniProt predicts a signal peptide or a membrane-spanning region. PROTAC: ubiquitination databases record sites on it.
Gene: Protein-coding gene on chromosome 17 (59,952,240 to 59,964,761, reverse strand). Ensembl gene ENSG00000189050.
Subcellular location: Endoplasmic reticulum membrane
Subcellular location (Human Protein Atlas): Nucleoli
Gene Ontology:
Molecular function: ubiquitin binding; ubiquitin protein ligase activity
Biological process: positive regulation of ERAD pathway; protein autoubiquitination; protein ubiquitination
Cellular component: endoplasmic reticulum; endoplasmic reticulum membrane
Genetic constraint (gnomAD): Loss-of-function variants: 21 observed, 33.66 expected, observed/expected ratio (o/e) 0.62, 90% interval 0.44 to 0.9. The upper end of that interval is the gene's LOEUF score, 0.9, which puts it in group 3 of 6, group 1 being the genes least tolerant of losing a copy. Missense variants: 317 observed, 392.62 expected, observed/expected ratio (o/e) 0.81, 90% interval 0.74 to 0.89. Synonymous variants: 116 observed, 137.05 expected, observed/expected ratio (o/e) 0.85, 90% interval 0.73 to 0.99.
Homologues: Orthologues: chimpanzee RNFT1 (99% identical), macaque RNFT1 (97% identical), pig RNFT1 (88% identical), dog RNFT1 (83% identical), guinea pig RNFT1 (82% identical), mouse Rnft1 (77% identical), rat Rnft1 (77% identical), tropical clawed frog rnft1 (53% identical), zebrafish rnft1 (45% identical), Drosophila melanogaster CG13605 (24% identical), Caenorhabditis elegans ZC13.1 (18% identical). Paralogues in human: RNFT2 (39% identical).
Diseases named in the same sentence as RNFT1 in open-access papers:
RNFT1 is named in the same sentence as 3 diseases in open-access papers, as found by Europe PMC text mining. Sharing a sentence is not in itself a finding about the gene and the disease. The quoted sentences say what the papers report.
breast carcinoma (6 papers, 2018 to 2025). "For TGFB2-dependent biomarkers, elevated TGFB2 mRNA expression is a prognostic biomarker associated with breast cancer patients that is correlated with improved OS outcomes at high expression levels of GDAP1, TBL1XR1, RNFT1, HACL1, SLC27A2, NLE1, and TXNDC16." (PMID 41373732, 2025). "Suppression of TRIM59, a highly expressed E3 ligase in breast cancer with metastasis, inhibits metastasis by inducing RNFT1-induced K63 ubiquitination of PDCD10." (PMID 36202787, 2022). "A recent study reported that depletion of TRIM59 suppresses breast cancer metastasis by promoting RNFT1-induced K63 poly ubiquitination and SQSTM1-directed autophagic degradation of PDCD10." (PMID 31600735, 2019). "The previous research indicated that RNFT1 may participate in the migration of breast cancer." (PMID 36750831, 2023). "TRIM59 suppresses K63 ubiquitination by RNFT1 and PDCD10 degradation by p62-mediated selective autophagy, which promotes migration of breast cancer cells." (PMID 36202787, 2022). "In cases dependent on TGFB2, increased mRNA expression of TGFB2 alongside higher levels of GDAP1, TBL1XR1, RNFT1, HACL1, SLC27A2, NLE1, or TXNDC16 was correlated with improved OS among breast cancer patients, of which four genes were upregulated in tumor tissues (SLC27A2, TXNDC16, TBL1XR1, GDAP1)." (PMID 41373732, 2025). "We detected the endogenous interaction between RNFT1 and PDCD10 in both breast cancer cell lines but not for IgG controls (IB: RNFT1, lanes 3 versus 1)." (PMID 30408026, 2018).
cancer (1 paper, 2024). A tumor composed of atypical neoplastic, often pleomorphic cells that invade other tissues. "Unfortunately, no reports on the function of the Ring Finger Protein, Transmembrane 1 (RNFT1), and Tetratricopeptide Repeat Domain 38 (TTC38) or their role in cancer have been found so far." (PMID 38163849, 2024).
tumor (1 paper, 2025). "Three genes (NLE1, HACL, and RNFT1) did not exhibit significant upregulation in tumor tissues." (PMID 41373732, 2025).